CD4 (CD4 molecule)
Diseases named in the same sentence as CD4 in open-access papers (continued):
Sharing a sentence is not in itself a finding about the gene and the disease.
infection (continued). "Although the percentage of CD103+CD4+ cells slightly increased, obvious increasing was only detected on week 5 after infection (P < 0.05)." (PMID 31775660, 2019). "It is relevant that in vaccine group A, the only group in which there was delayed infection, there was a correlation between CD4 cytokine production and the number of SIV exposures required for infection." (PMID 31413132, 2019). "Unlike global IL-4Rα−/− mice infected with L. donovani that developed significantly higher parasite burdens than wild-type mice in this and previous studies, CD4+ T cell specific IL-4Rα−/− mice were by comparison resistant to infection." (PMID 31475014, 2019). "The ‘shock and kill’ strategy entails activation of HIV-1 expression to allow latently-infected resting memory CD4+ T-cells to die from viral cytopathic effects and/or host cytolytic immune effectors, while controlling new infections via HAART." (PMID 31487807, 2019). "The effect of inflammatory responses mediated by CD4+ T cells plays an important role in anti-intracellular parasitic pathogen infection." (PMID 31998324, 2019). "Most CD4+ T cells from control subjects and patients with infections only expressed RORγt, with very few CD4+ T cells expressing T-bet." (PMID 31658288, 2019). "Further, in vitro studies have shown that DC can be infected cell-free with high concentrations of isolated VBs, which then mediate efficient cell-cell contact-dependent infection of CD4+ T-cells." (PMID 31708905, 2019). "Half of skin CD4+ T cells persist in peri-follicular clusters that accurately equilibrate with the blood lymphocytes during steady state, and infection can increase the immune cell content of these clusters." (PMID 31156652, 2019). "Reporter gene expression was stable for over 10 days during progressive infection in cultured primary CD4+ T cells and for at least two weeks in humanized PBMC mice (Hu-PBL)." (PMID 31805155, 2019). "In the CD4+ T cell-depleted group, production of IL-2 and IL-10 were decreased in the early stage of infection, and production of IL-17 and TNF-α was decreased in both the early and late stages." (PMID 31608052, 2019). "Lastly, HIV latency is best studied by infection of activated CD4 T cells and return to a quiescent and resting state, followed by proviral reactivation of purified resting CD4 T cells." (PMID 30786885, 2019). "In contrast, IL-2-producing CD44+CD4+ T cells were already detectable on day 3 but were most abundant on day 15 post-infection." (PMID 30677097, 2019). "Briefly, CD8+ T cells and macrophage depletion prior to a secondary infection significantly impairs Pneumocystis clearance compared with CD4+ depleted mice, which clears infection within 48 h, comparable to immunocompetent mice." (PMID 31010170, 2019). "Collectively, these results suggest that generation of IL-3–secreting CD4+ T cells in vivo is restricted to infection or vaccination through barrier surfaces, such as skin and mucosa." (PMID 31356170, 2019). "Another well studied retrovirus, HIV-1, has been shown to down regulate the expression of its receptor molecule (CD4) post infection." (PMID 30897179, 2019). "PHA-stimulation resulted in significantly more infection than all other conditions (p < 0.001), with approximately 25% of CD4+ T cells infected." (PMID 31396221, 2019). "Infection with influenza A virus also leads to CD4+ and CD8+ T-cell responses, which are essential for clearance of the influenza infection." (PMID 30796267, 2019). "LysMCre+Ifnar1fl/fl mice were treated with isotype control or anti-CD4 Ab, and serum samples were taken on day 7 post-infection for analysis of IgM and IgG reactivity to ZIKV E protein by ELISA." (PMID 30677097, 2019). "In agreement with our findings, the NETs were also able to capture RSV and to inhibit its infection in the A549 lung epithelial cells as well as HIV-1 in the CD4+ T cells, clearly demonstrating their antiviral role." (PMID 32082301, 2019).
infection (continued). "In the NALTs of inbred mice, CD4+ T cells were similarly found to proliferate upon infection with GAS, producing IFN-γ, IL-6, and IL-17." (PMID 31119108, 2019). "We thus assume that infection of CD4+ T cells is determined by the number of contacts/encounters of infected cells and health CD4+ T cells." (PMID 31532803, 2019). "Although the CD4+ T-cell count approximately 3 months after infection was correlated with viral control in this cohort, it would have been informative to describe any immunological discrepancies prior to HIV acquisition." (PMID 30938435, 2019). "The percentage of human CD4 + T cells in mice was determined in blood by flow cytometry at 2, 6, 11, and 15 weeks and showed decline after infection." (PMID 31266936, 2019). "Re‐analysis of published RNA‐seq studies confirmed these transcriptomic signatures, demonstrating the reproducibility of these results in CD4 + T cells from different donors and after infection with different HIV strains." (PMID 31339004, 2019). "The original differences between CD3+ and CD4+ observed in PBMCs from males and females grew significantly during infection (p = 0.0002, p < 0.0001, respectively)." (PMID 31477151, 2019). "L. donovani-specific IgG1 and IgG2a levels and total serum IgE levels were measured in CD4+ T cell specific IL-4Rα−/− mice, wild-type control and global IL-4Rα−/− mice at days 15, 30, and 56 post-infection." (PMID 31475014, 2019). "Most participants (91.7%) had CD4 count less than or equal to 500 cells/mm3, and the average duration of the infection was 2.2 years." (PMID 31464596, 2019). "The infection rate in trans-infected CD4+ T cells was slightly lower to the infection rate of CD4+ cells when cocultured with CECs but significantly higher than infected CD4+ T cells in the absence of CECs." (PMID 31772057, 2019). "Already 6 days post infection (p.i.), Treg frequency of CD4+ T cells in the spleen increased in Δ/Δ animals to about 28%, while WT animals had normal Treg frequencies at that time point (about 9%)." (PMID 30962454, 2019). "These Envs are unable to bind CD4 with high affinity and to signal stabilizing acetylated α-tubulin, correlating these facts with the low fusion, infection, and replication activities of viruses from this LTNP-EC cluster." (PMID 31736889, 2019). "Previously, we observed there are significant increases in the frequency and number of CD4+Foxp3+ Tregs during acute P. chabaudi AS infection in B6 mice followed by a transient decrease until the infection is resolved." (PMID 30915078, 2019). "The frequency of nTregs in advanced stage patients with CD4+ T counts <200 cells/μL was decreased compared with those detected in patients in the other stages of infection, as well as in healthy uninfected individuals." (PMID 31681335, 2019). "DC can efficiently mediate trans-infection of neighboring CD4-positive T-cells by trapping HIV-1 on their cell surface using DC-SIGN, which binds N-glycan of Gp160, or CD169, which binds glycosphingolipid of envelope." (PMID 31638994, 2019). "In our previous work, we have shown that IL-3–producing CD4+ T cells develop following vaccination with BCG by s.c. route or infection with M. tuberculosis by aerosol." (PMID 31356170, 2019). "We used a combination reporter virus system that allowed us to sensitively and specifically track the kinetics of infection of resting CD4+ T cells after viral entry and before any de novo viral protein production." (PMID 30943397, 2019). "Trichinella is a fascinating infection model for induction and regulation of differentiation of various CD4+ T cells subsets for adaptive immune systems in response to infection." (PMID 31703440, 2019). "These foci likely contain cells at multiple stages of infection with variable amounts of surface-expressed CD4 and variable levels of virus production." (PMID 30903381, 2019).
infection (continued). "Oct1/Pou2f1 is a POU-domain transcription factor that in mice is dispensable for T cell development and response to primary infection but is important for the formation of CD4+ central memory cells." (PMID 31266507, 2019). "In peripheral blood, broadly reactive CD4+ T cells were detected early during this infection but became undetectable in patient cohorts with chronic infection, even after viral loads diminished." (PMID 31379821, 2019). "We therefore sought to test the contribution of SmCB1 activity to CD4+ T cell induction during natural infection and to test the immunostimulatory properties of active SmCB1 directly." (PMID 30653492, 2019). "Much less is known about the differentiation of memory CD4+ T cells compared to CD8+ T cells, in part because of the ability of naïve CD4+ T cells to adopt different effector cell fates that are uniquely regulated and are elicited by different infections." (PMID 31379821, 2019). "(C) Expression of cell surface SBP-∆LNGFR and CD4 on primary T cells 24 or 48 hr post-infection with HIV-AFMACS." (PMID 30857592, 2019). "The HIV-infected cocultures exhibited reduced CD4+ T-cell growth at weeks 3–5 post infection compared to autologous uninfected cocultures." (PMID 30761146, 2019). "In this way DCs serve as virus reservoirs to mediate trans-infection of CD4-positive T cells, thereby facilitating spread of HIV-1 to the lymph nodes." (PMID 31354736, 2019). "It appears that CECs, regardless of their origin, have similar immunological properties and adhere to HIV and enhance its infection/replication in CD4+ T cells in vitro." (PMID 31772057, 2019). "Cell lines expressing human CCR5 and different primate CD4 receptors were then infected with this BG505 virus (similar infection results were obtained in cell lines expressing matched CD4 and CCR5 from each species)." (PMID 31181085, 2019). "There have been a number of studies that have reported individual HA epitopes that are recognized by CD4 T cells in both human and mouse models of infection and vaccination." (PMID 31694141, 2019). "During the infection challenge, they also tracked the number of CD4+ and CD8+ T cells, common markers of an immune system actively clearing infection." (PMID 31766664, 2019). "Ultimately, the infection leads to activation of CD4+ and CD8+ T cells that facilitate clearance of the primary infection and provide protection against subsequent exposures." (PMID 30914953, 2019). "According to the trends, CD4+ T levels were decreasing at 30 h after infection, while CD8+ T levels were on the rise." (PMID 31855175, 2019). "With progression of infection, less CD4 is expressed on the surface of HIV-1-infected cells through the combined effects of the viral Nef and Vpu proteins." (PMID 30842326, 2019). "Proliferating Ki67+ CD4 T cells in pigs were detected as early as 4 days post infection (dpi) in the draining TBLN." (PMID 30804933, 2019). "This binding has been shown to neutralise HIV and prevent direct infection of a CD4+ T cell line, PM1." (PMID 30293076, 2019). "IL-17, mainly produced by the Th17 subset of CD4+ lymphocytes, plays an important role in the mucocutaneous candidiasis, positively correlating with the infection burden, namely, higher IL-17 levels correspond to a more serious infection burden." (PMID 30621597, 2019). "CD4 +T cell resistance to infection in prospective single cycle assay, specific to R5-tropic viruses in a subset of EC/VCs." (PMID 30964004, 2019). "Ex vivo APC from chronic HIV-infected MACS participants before and after initiation of ART, were also loaded with HIV R5-tropic HIVBal and tested for trans infection against autologous or heterologous CD4+ T lymphocytes." (PMID 31304185, 2019). "We next wanted to determine if infection of DCs by S. aureus impaired the activation of CD4+ T cells." (PMID 30602580, 2019).
infection (continued). "The CD4+/CD8+ T cell ratio gradually increased in the liver as the infection dose increased, and it was markedly lower in LDG than in MDG and HDG at 2 weeks (p < 0.001; p < 0.001)." (PMID 31873157, 2019). "In a separate study, IL-2 treatment of NHP in early-stage infection expanded Foxp3+ Tregs, and CD4+/CD8+/γδ T effector cells." (PMID 31572365, 2019). "Candidate variables were sex, marital status, educational status; Years lived with HIV, eating difficulty, HAART status, CD4 count, infection with intestinal parasites and BMI." (PMID 31596865, 2019). "Independently of the viral entry to DCs or productivity of the infection, co-culture of CD4+ T cells with R5-infected cDCs resulted in a higher viral expansion than co-culture with X4-infected cDCs." (PMID 31708924, 2019). "The most predictable clinical markers for the development of bNAbs are duration of infection, high viral load, and in some cohorts low CD4+ T cell count." (PMID 31027215, 2019). "Transfections of histone deacetylase 1 (HDAC1) expression vectors and/or specific siRNA were conducted in HeLa-CD4 and 293 T cells followed by infection with fully infectious NL4–3 and luciferase-expressing pseudotyped viruses or by proviral DNA transfection." (PMID 31744547, 2019). "During this period CD4+ T cell counts are sometimes similar between persons with recent and established infection." (PMID 31125356, 2019). "These claims are reinforced by our prior studies demonstrating up to a 10-fold increase in viral restriction at two independent multiplicities of infection in CD4 + T cell lines with LASER ART when compared to conventional native drugs." (PMID 31266936, 2019). "On the other hand, this established a new methodology of stably maintaining HIV in culture because CD4 T cells doubly infected by HTLV-1 and HIV would remain viable and keep producing HIV whereas an infection by HIV alone would kill the target CD4 T cells." (PMID 30854194, 2019). "For example, CD4+ T cells have been confirmed to be essential for the generation of optimal antibody responses during infections with yellow fever virus, vaccinia virus, coronavirus, or vesicular stomatitis virus (VSV)." (PMID 30828337, 2019). "LdCen/−2W infection resulted in significantly higher IL-2R+ CD4+ T cells as was observed in our previous studies." (PMID 31608064, 2019). "A later study using a vaccine strain model of infection demonstrated that both CD4 and CD8 T cells are important for controlling the infection, even though CD8 played a more dominant role." (PMID 31119107, 2019). "The frequency of FV-mWasabi-infected Gr1+ myeloid cells also increased in this phase of the infection, and importantly, we saw an increasing frequency of infected B cells of up to 20% and low frequencies of infected CD4+ T cells." (PMID 30782653, 2019). "In contrast, the ability of CD4+Foxp3+ Tregs to migrate to CXCR3 chemokines decreased significantly with infection." (PMID 30915078, 2019). "Recent studies suggest that exosomes from HIV-1 infected DCs can not only activate and infect resting CD4+ T lymphocytes via trans-infection, but also reach and reactivate the HIV-1 reservoir, further boosting the progression of infection." (PMID 31708924, 2019). "A cellular analysis on day 7 after infection indicated that there was an enhanced antigen-specific CD8 (OT1 peptide) immune response in Il17d−/− mice while CD4 (LLO peptide) response was similar between WT and Il17d−/− mice." (PMID 31244826, 2019). "A slight depletion of CD4+ T cells was observed by 6 weeks of infection as seen in our previous reports." (PMID 30832693, 2019). "Using this novel model, they were able to show that the monocyte/macrophage reservoir can sustain infection independently of CD4+ T cells and that viremia is undetectable in cART treated mice compared to cART-naïve mice." (PMID 31297114, 2019).
infection (continued). "Further, the frequency of pulmonary Treg cells among the antigen-experienced (CD49d+CD11ahi) CD4 T cell pool in the lungs of BALB/c mice is first significantly elevated above naïve lungs at day seven post-infection and peaks at days 7 and 8 post-infection." (PMID 31632414, 2019). "After the infection, a progressive decline of CD4 + cells consequently leads to the failure of the immune system function and the development of opportunistic infections that usually lead to death." (PMID 31561445, 2019). "If MRPs are responsible for basolateral transport of TFV, we would expect that after MRP blockade less TFV would be released into the CM resulting in increased infection of CD4+ T cells by HIV." (PMID 30755713, 2019). "It has also been described that the amyloid fibrils in semen, and the heparan sulfate on spermatozoids can bind the virus, enhancing the infection of CD4+ T cells or DC, respectively." (PMID 30787929, 2019). "A similar but distinct form of HIV-1 trans infection occurs between CD4+ T lymphocytes, where the level of viral replication in the trans-infected T cells is lower than in T cells trans-infected by APCs." (PMID 31304185, 2019). "We found that the intensity of the viral reporter fluorescence in resting CD4+ TN cells was lower than in resting CD4+ TM cells at 3 days post-infection." (PMID 31036079, 2019). "Macrophages can be infected by cell-free HIV or cell-to-cell transmission from infected CD4 T cells via virologic synapses, or by selective phagocytosis of infected CD4+ T cells, leading to efficient infection." (PMID 31616434, 2019). "Using the small intestinal dwelling helminth T. spiralis, we observed increased TGFβ signalling in CD4+ T-cells and production of Th17 cells late in infection." (PMID 30998782, 2019). "Next, we examined if the TcG2/TcG4-induced activation of antigen presenting cells modulate the splenic CD4+T cell responses in mice after immunization and challenge infection." (PMID 31293599, 2019). "Mouse models have demonstrated that infection produces a strong CD4+ T-cell and type 2 cytokine driven transient inflammation culminating in worm expulsion around day 15 post-infection (p.i.)in C57BL/6 mice." (PMID 30998782, 2019). "Although preexposure to anti-CD35 antibody moderately reduced HIV trans-infection from RBCs of CD4+ T cells, rCCL-5 at 100 nM almost abolished the ability of RBCs to trans-infect CD4+ T cells with HIV-1." (PMID 31772057, 2019). "We have shown that infection of naïve mice with B. pertussis induces CD4 TRM cells that are maintained in the lung after bacterial clearance." (PMID 30866771, 2019). "Since the likelihood of escaping infection is the same as the probability of no contacts during the CD4+ T cell’s lifetime, the probability of the CD4+ T surviving infection is given by exp(−β1Vt)." (PMID 31532803, 2019). "Lastly, we evaluated HIV-1 trans-infection from differently matured DCs to autologous, stimulated CD4+ T cells as revealed by a co-culture with T cells." (PMID 31178863, 2019). "Despite the diverse disease outcomes, IDO inhibition induced some phenotypes that were shared by resistant and susceptible mice: the increased migration of DCs and CD8+ and CD4+ T cells to the site of infection concomitantly with reduced influx of Treg cells." (PMID 30067137, 2019). "For example, miR-451 suppresses CD4+ T cell proliferative to Plasmodium parasite responses and miR-451−/− mice increased immune responses to infection." (PMID 31238581, 2019). "During early infection, defined by infected cells expressing CD4, levels of CD20 were notably higher than during late infection, as defined by cells with marked downregulation of the CD4 receptor." (PMID 31420544, 2019). "Studies on DCs activated by different maturation factors showed that iDCs and CD40L-induced mDCs were more susceptible to productive infection and lead to cis-infection, while LPS and TNF-α-induced mDCs mediated efficient trans-infection of CD4+ T cells." (PMID 31708924, 2019).